KLF4 (KLF transcription factor 4)
Diseases named in the same sentence as KLF4 in open-access papers (continued):
Sharing a sentence is not in itself a finding about the gene and the disease.
tumor (continued). "MiR-10b overexpression accelerated PCC proliferation and tumor growth; miR-10b enhanced the stimulatory effects of EGF and TGF-β on cell migration and EMT, decreasing the expression of RAP2A, EPHB2, KLF4 and NF1." (PMID 29254283, 2017). "While Bulun’s group have reported CD34+/CD49+ cells in myometrial SP which also express KLF4, NANOG, SOX2 and OCT-4 as the possible myometrial stem cells and also tumor initiating cells." (PMID 28438190, 2017). "Our results show that only KLF4, NOTCH1, and OCT3/4 were down-regulated in the whole tumor compared with normal kidney samples." (PMID 29383160, 2017). "SP cells showed higher tumor-initiating ability and SP cell showed higher expressions of stem cell-related genes including SOX2, ALDH1A1, KLF4 and NANOG, indicating that SP cells are enriched with CSCs/CICs." (PMID 27418136, 2016). "KLF4 expression is negatively correlated with MUC2 in these signet ring carcinomas (‘T': tumor tissue)." (PMID 27277677, 2016). "Krüppel-like factor 4 (KLF4) is a zinc-finger transcription factor and is a potential tumor suppressor in GI cancers." (PMID 27277677, 2016). "In addition, p21Cip1 coexpression may determine the tumor suppressor or oncogenic function of KLF4." (PMID 27022622, 2016). "Krüppel-like factor 4 (KLF4) is a transcription factor that contributes to diverse cellular processes and serves as a tumor suppressor or oncogene in various cancers." (PMID 27153563, 2016). "Krüppel-like factor 4 (KLF4), a transcription factor involved in both tumor suppression and oncogenesis in various human tumors, is subject to alternative splicing that produces KLF4α." (PMID 27323810, 2016). "To confirm that KLF4 has a tumor suppressive effect in vivo, we established a xenograft model in BALB/c nude mice with SCC15/KLF4 cells." (PMID 26517087, 2015). "Taken together, our results point to a critical role for aberrant KLF4 regulation by PRMT5 in genome stability and breast carcinogenesis." (PMID 26420673, 2015). "Conversely, KLF4, CXCL2, MAPK3 and TIMP4 were up regulated in normal samples compared to tumor tissues." (PMID 26498364, 2015). "DCLK1 knockdown resulted in decreased expression of OCT4 (>30%), KLF4 (>45%), LIN28 (>40%), and NANOG (>50%) in tumor xenografts." (PMID 26468984, 2015). "KLF4 (Kruppel-like factor 4), which is also called EZF (Epithelial zinc finger protein), is a transcription factor that participates in both tumor suppression and oncogenesis." (PMID 26110566, 2015). "Analyses on 27 primary tumours confirmed the expression of some pluripotency genes (for example, OCT4 and KLF4) and endodermal stem cell traits (for example, SOX17 and PDX1) paralleling what was observed with the transplantable tumour line." (PMID 26437858, 2015). "Given that KLF4 appears to function as a tumor suppressor in HCC, we next determined what physiologically stimulates FBXO22 to interact with and stabilize KLF4." (PMID 26087183, 2015). "Our observations indicated that KLF4 plays Janus-faced roles in OSCC, acting as both a tumor suppressor and as an oncogene." (PMID 26517087, 2015). "Among all the identified genes, we focused on KLF4 because it was reported to be significantly downregulated in ALL and functions as a tumor suppressor in B-cell hematological malignancies." (PMID 25037230, 2014). "MiR-10b is a potent pro-metastatic metastamiR and previous studies have shown that miR-10b targets several tumor suppressors such as, HOXD10, KLF4, TIAM1 and others." (PMID 25426550, 2014). "The identification of pluripotency factors such as SOX2, OCT4, KLF4 and LIN28A in human cancer suggests a close relationship between tumor formation and the process of reprogramming mature cells to a more primitive type." (PMID 23846349, 2013). "The results revealed that the expression levels of Oct4, Sox2, Klf4, c-Myc and Nanog in HCC specimens were signifcantly higher than those in the corresponding adjacent non-tumor tissues." (PMID 23599755, 2013).
tumor (continued). "Epithelial-like MM189 PB-Klf4 and BL322 PB-Klf4 cells were generated from tumor suppressive Kruppel-like factor 4 (Klf4)-expressing mesenchymal-like MM189 and BL322 cells." (PMID 24196357, 2013). "Consistent with a role as a tumor suppressor in HCC, analysis of the public microarray databases from Oncomine revealed reduced KLF4 expression in human HCC tissues in comparison with normal liver tissues in 3 out of 4 data sets." (PMID 22937066, 2012). "Globally, KLF4 and KLF6 are considered as tumor suppressor gene, whereas KLF5 promotes cell proliferation." (PMID 20119532, 2009). "Rather than acting solely within tumor cells, KLF4 exerts many of its effects indirectly by shaping the behavior of TME components." (PMID 41532367, 2026). "Moreover, CD10 (MME) positive myCAFs were found as a novel tumor suppressed CAF subclusters, while KLF4 positive and TIAM1 positive iCAFs were considered as tumor promoted CAF subclusters." (PMID 40303408, 2025). "The absence of KLF4 impairs CD8+ T cell differentiation and function, making them more susceptible to exhaustion and weakening the anti-tumor response." (PMID 39995670, 2025). "Moreover, after DNA damage, cells expressing Klf4 exhibited increased levels of BRCA1 and Rad51, known tumor suppressor genes." (PMID 40699616, 2025). "Furthermore, cell lines obtained from such metastases retained the expression of some stemness factors (e.g., SOX2, KLF4, c-MYC) and were able to form tumorspheres in vitro, confirming the tumor stem cell behavior of these isolated subpopulations." (PMID 40806546, 2025). "Additionally, some studies have indicated that KLF4 can activate and reactivate exhausted CD8+ T cells, promoting their differentiation into transient effector subpopulations and enhancing their anti-tumor activity." (PMID 39995670, 2025). "As KLF4 mediates tumor-suppressive effects following ACTL6A depletion, we examined whether ectopic KLF4 expression could reproduce these phenotypes in CRC cells." (PMID 40877226, 2025). "To evaluate the stemness role in ITAC prognosis, we analyzed, for the first time, the expressions of the Yamanaka factors KLF4, c-MYC, SOX2, OCT4, and NANOG in a cohort of patients with ITAC and investigate their possible roles in influencing tumor properties and survival." (PMID 41463190, 2025). "Furthermore, we found that patients with tumor overexpressing KLF4 and NANOG had significantly higher OS compared to those who showed lower KLF4 and NANOG expressions (log-rank, p = 0.049, and p = 0.0005, respectively)." (PMID 41463190, 2025). "The underlying mechanism may involve an increase in KLF4 expression on CD8 tumor-infiltrating lymphocytes (TILs) and an elevated number of transient effector CD8+ T cells expressing KLF4." (PMID 39995670, 2025). "The coordinated downregulation of KLF4, OLR1, CSF3, WIF1, RAMP3, and AGER, may impair tumor-suppressive mechanisms, thereby facilitating cancer progression, including enhanced tumor growth, migration, invasion, and metastasis." (PMID 40797277, 2025). "Although such studies suggest that KLF4 acts as a tumor suppressor in T‐ALL, it remains unclear whether KLF4 regulates the differentiation of T‐ALL cells." (PMID 40354086, 2025). "Additionally, noncoding RNAs such as lncRNAs (CRNDE, MIR210HG, SNHG9, TUG1) and circRNAs (CDR1) interact with miRNAs (miR-7–5p, miR-608) to modulate the expression of downstream targets such as KLF4 and FOXO6, further influencing tumor stemness and malignancy." (PMID 41393242, 2025).
tumor (continued). "In contrast, goblet cell markers, such as KLF4, mucin 2 (MUC2), and SAM pointed domain-containing Ets transcription factor (SPDEF), were consistently downregulated in tumor tissue, aligning with the literature describing a reduced goblet cell population in the neoplastic intestinal epithelium." (PMID 41303610, 2025). "In adaptive immunity, KLF4 inhibits the proliferation of CD8+ T cells and B cells through transcriptional repression of pro-survival and cell cycle-promoting genes such as NOTCH1 while also acting as a tumor suppressor." (PMID 40831570, 2025). "In this study, for the first time, we found that Tregs enhanced the ‘stemness’ of HCC cells, demonstrated by increased TICs ratio, upregulated expression of TICs-related genes CD133, Oct3/4, Sox2, c-Myc, Klf4, Nanog, CD13, EpCAM, elevated tumor sphere formation, and tumorigenic ability." (PMID 39073490, 2024). "However, the expression of CD133/PROM1, OCT4/POU5F1, KLF4, and MYC occurred more frequently compared to EPCAM-negative tumor spots." (PMID 39456890, 2024). "Unlike the other pluripotency genes, Klf4 has been observed to possess a tumor-suppressive role in gastric and colorectal cancers." (PMID 38247819, 2024). "In GBM, KLF4 has been shown to activate Notch and its downstream target Nestin, thereby establishing proneural GSC identity and contributing to the survival of GSCs and tumor growth." (PMID 39273014, 2024). "The intricate network of TFs, including SOX2, OCT4, NANOG, KLF4, c-MYC,β-catenin, STAT3, NF-κB, HIF-1α and YAP/TAZ, is central to the maintenance of the stem-likeproperties of GSCs, which in turn drive tumor heterogeneity, therapeutic resistance, andrecurrence." (PMID 38716541, 2024). "Considering the intimate connection between epithelia-mesenchymal transition (EMT) and cancer stemness, we also found the expression of STAT3 and KLF4 were decreased in ADCY5 overexpressing cells (P < 0.001), suggesting ADCY5 was capable of inhibiting stemness of tumor cells." (PMID 39319137, 2024). "Furthermore, the increased expression of Cdx2, and other differentiation-driving transcription factors like Klf4 and the WNT antagonist, Ndrg1, in BLM tumors push the tumor stem cells toward the various differentiated lineages." (PMID 38893159, 2024). "KLF4, in turn, represses the expression of the interferon-induced transmembrane (IFITM) protein IFITM3, a gene that is overexpressed in human colorectal cancers and which contributes to tumor growth and metastasis." (PMID 38067370, 2023). "Furthermore, considering the significance of KLF4 and KLF5 in tumor formation and development, efforts to understand their context-dependent role and downstream effectors, interacting proteins, and response to chemotherapy drugs are essential." (PMID 37173904, 2023). "Besides KLF4 we also detected PARP1, which was recently described to inhibit MICA expression on AML cells as part of the tumor immune evasion strategy which validates the approach." (PMID 37143070, 2023). "At every time point imaged, the level of tumor burden was significantly lower in the KLF4 knockout cell line than the non-target control line." (PMID 37938582, 2023). "KLF4, as an antiproliferative factor in differentiated epithelium, knockdown significantly reduces TWIST1-induced metastatic activity in vitro and in vivo and decreases tumor initiation capacity." (PMID 37598158, 2023). "Whether KLF4 can signal between tumor cells via exosomes remains a mystery, although exosomes are found to contain pluripotency genes (OCT4, SOX2, KLF4, C-Myc and Nanog) during embryonic development." (PMID 37031197, 2023). "KLF4 is a transcription factor that plays significant tumor-suppressive roles in the pathogenesis and progression of HCC, such as promoting tumor differentiation, suppressing epithelial-mesenchymal transition, and restraining tumor growth and metastasis." (PMID 36936440, 2023).
tumor (continued). "Our initial data suggested KLF4 is not a marker of tumor stage, size, location, differentiation, or metastasis." (PMID 37173904, 2023). "Interestingly, in tumors high tumor abundance, SMAD3 and KLF4 high, and PPARG low expression, were significantly associated with poor prognosis, albeit small sample size." (PMID 38129585, 2023). "Thus, increased PTEN, KLF4, and SLURP1 expression points on activation of anti-oncogenic pathways in the tumor." (PMID 37854069, 2023). "We found that CD8-GNLY effector T cells in high tumor infiltration group displayed increasing level of the serine/threonine kinase PIM family (PIM2 and PIM3), NR4A2/3, KLF4/6, BCL2, GPR183 and COTL1 compared to the ones from HD and low tumor infiltration group." (PMID 36532059, 2022). "KLF4 inhibits the expression of MHC and thus inhibits tumour development." (PMID 35177016, 2022). "Downregulated genes include: 1) Immune system activators, such as CD86; 2) blood tumor suppressors ID2 and KLF4; 3) CEBPB, CEBPB is a BCR/ABL negative regulator gene, which can inhibit the proliferation of BCR/ABL-positive cells, and promote cell differentiation." (PMID 36699453, 2022). "We observed that histone demethylase, Kdm3a, was downregulated in tumor cells treated with Oct4 CM and c-Myc CM, but it was not altered by the treatment with Sox2 CM and Klf4 CM." (PMID 35547745, 2022). "After 2 weeks, the tumor size was measured, and the expressions of PTEN and KLF4 were detected." (PMID 35637651, 2022). "KLF4 and KLF5 were downregulated and played tumor suppressor roles in RCC." (PMID 35787628, 2022). "Here, we set up the hypothesis, that replacement of KLF4 with Slug and vice versa regulates the cadherin switch, which is essential for the regulation of invasive, proliferative/adhered forms of HNSCC tumor cells." (PMID 35219646, 2022). "Importantly, tumor xenograft assay showed that MEX3A knockdown significantly suppresses tumor growth, while KLF4 knockdown rescues MEX3A inhibition-induced suppression of tumor growth (Figure EV4A-C)." (PMID 36276637, 2022). "Knockdown of KLF4 and BMI1 reduced the number and size of tumor sphere formation and tumor-initiating ability, suggesting that both KLF4 and BMI1 may contribute to inducing stem-like property and metastasis by TWIST1-JAGGED1-NOTCH-KLF4 signaling in HNC." (PMID 36553636, 2022). "Three URs (ARHGAP21, KLF4, TBK1), among those that discriminated responding and non responding patients in the baseline tumor samples, lost significance in subsequent biopsies, possible reflecting the shift in the transcriptomic programs of the neoplastic lesions occurring as result of therapy." (PMID 36397155, 2022). "Although our study showed that the expression of KLF4 is not related to the prognosis of the tumours included in the study, we found that high expression of KLF4 predicted a trend of better prognosis." (PMID 35177016, 2022). "Moreover, we confirmed the stabilization effects of HPV-virus transcripts on KLF4 in UPCI-SCC090 cells and in HPV-positive tumor tissue samples." (PMID 35219646, 2022). "Positive correlation of TCFL5 and SOX2 was found in the normal region adjacent to the tumour samples but not in healthy tissue or tumour samples, while KLF4 negatively correlated with TCFL5 in tumour samples." (PMID 34623757, 2022). "A typical example is Krüppel-like factor 4 (KLF4), which binds preferentially to methylated sequences and activates rather than represses transcription of related genes and tumor development." (PMID 36139427, 2022). "Together with the positive correlations of DUB3 with KLF4 in human HCC tissue samples and overall survival in HCC patients, our findings suggest that activating the DUB3/KLF4 loop may prevent tumor growth and chemoresistance in HCC." (PMID 35383144, 2022). "According to these results, the expression levels of NR3C2, KLF4, CASZ1, FOXD2, ATOH1, and RORC reduce in CRC and may function as tumor suppressors." (PMID 36344988, 2022).
tumor (continued). "The suppression of KLF4 significantly increased LDHA expression and was correlated with the development and progression of cancer, whereas overexpression of KLF4 inhibited LDHA expression, aerobic glycolysis, and tumor size in in vivo and in vitro models." (PMID 36551514, 2022). "We presented in this study that two of the Yamanaka factors, Oct4 and c-Myc, can be used to convert the secretome of tumor cells into tumor-suppressive, while two other factors, Sox2 and Klf4, failed to induce tumor-suppressing capabilities." (PMID 35547745, 2022). "Similar to KLF4, the biological impact of SOX2 in tumor cells is dependent on tumor type." (PMID 36553636, 2022). "This study showed that the expression of KLF4 was not related to the prognosis of the tumours that were included in the study." (PMID 35177016, 2022). "The overexpression of Oct4 and c-Myc in tumor cells reduced the expression of downstream oncogenic genes in parental tumor cells but the overexpression of Sox2 and Klf4 did not." (PMID 35547745, 2022). "Although LY2228820 only slightly inhibited tumor growth rate, it markedly inhibited paclitaxel-induced increases of ALDH+ and mammosphere-forming cells and of expression of Nanog, Sox2, and Klf4." (PMID 35401817, 2022). "Furthermore, it was reported that tumor-derived SHH directly acts on TAMs to promote M2 polarization, mediated by the transcription factor Krüppel-like factor 4 (Klf4)." (PMID 35860588, 2022). "The result suggests that histone methylation is altered by the newly identified extracellular tumor suppressors, which were enriched in CM by the overexpression of Oct4 and c-Myc and not by the overexpression of Sox2 and Klf4." (PMID 35547745, 2022). "The so-called inflammatory CAFs (iCAFs) that express ALDH1A1, KLF4, LEPR, and CXCL12 were distributed across the areas that contain both tumor and immune-stromal cells, whereas the myofibroblast CAFs were enriched only in the tumor cell-enriched area." (PMID 36376874, 2022). "The results showed that deguelin could effectively inhibit tumor growth and upregulate the expressions of PTEN and KLF4 in tumor tissues." (PMID 35637651, 2022). "Similarly, we observed that si-BMI1, si-KLF4, combination therapy, and PTC-209 all significantly inhibited tumor cell invasion compared with each control group (*p < 0.05; **p < 0.01)." (PMID 33828977, 2021). "As a result, several hub DEFs with maximum intramodular connectivity were identified (e.g., SOX4, EGR1, LEF1, FOS, MITF, KLF4, TCF7, and KDM6B), which might involve CD248-mediated tumor-promoting regulation in CAFs." (PMID 34970489, 2021). "Although this research is not a comprehensive analysis of KLF4′s metabolic function specific to cancer cells, we used cells lacking KLF4 to find that KLF4 has tumor-suppressing properties with respect to metabolism." (PMID 33917010, 2021). "The role of KLF4 in hematological malignancies has not been clearly defined because of its dual role as tumor suppressor and an oncogene depending on the leukemic cell context." (PMID 33659038, 2021). "Aberrant overexpression of SF3B4 inactivates Krüppel-like factor 4 (KLF4), a tumor suppressor." (PMID 35008179, 2021). "This tumor suppressor is progressively lost in the formation and progression of CRC32, but the expression patterns of KLF4 in drug-resistant CRC and its function remain unclear." (PMID 33986248, 2021). "Additionally, XIST also promoted EMT and tumor stemness via regulating the miR-133a/SOX4 and miR-152-Krüppel-like factor 4 (KLF4) axes, respectively." (PMID 34322395, 2021). "Furthermore, increases in the properties of stem cells were measured by assessing the capacity for tumor formation and performing transcriptional analysis of the OSKM genes (OCT4, SOX2, KLF4 and MYC), NANOG, NES and PROM1." (PMID 34364391, 2021).